NEK3 (NIMA related kinase 3)
Description:
Protein kinase which influences neuronal morphogenesis and polarity through effects on microtubules. Regulates microtubule acetylation in neurons. Contributes to prolactin-mediated phosphorylation of PXN and VAV2. Implicated in prolactin-mediated cytoskeletal reorganization and motility of breast cancer cells through mechanisms involving RAC1 activation and phosphorylation of PXN and VAV2.
Synonyms: HSPK36; MGC29949
Tractability: Small molecule: a high-quality ligand is known; it belongs to a druggable protein family. PROTAC: it is named in the literature on targeted protein degradation; ubiquitination databases record sites on it; its protein half-life has been measured; a small molecule that binds it is known.
Target class: Kinase; Protein Kinase; Other protein kinase group; Other protein kinase NEK family; Other protein kinase Nek1; Enzyme
Gene: Protein-coding gene on chromosome 13 (52,132,639 to 52,159,600, reverse strand). Ensembl gene ENSG00000136098.
Subcellular location: Cytoplasm; Cell projection, axon
Subcellular location (Human Protein Atlas): Microtubules; Cytokinetic bridge; Mitotic spindle; Plasma membrane; Primary cilium
Gene Ontology:
Molecular function: protein binding; protein serine/threonine kinase activity; ATP binding; protein kinase activity; protein serine kinase activity
Biological process: mitotic cell cycle; protein phosphorylation
Cellular component: nucleus; axon; cytoplasm
Genetic constraint (gnomAD): Loss-of-function variants: 30 observed, 43.52 expected, observed/expected ratio (o/e) 0.69, 90% interval 0.51 to 0.94. The upper end of that interval is the gene's LOEUF score, 0.94, which puts it in group 3 of 6, group 1 being the genes least tolerant of losing a copy. Missense variants: 441 observed, 439.48 expected, observed/expected ratio (o/e) 1, 90% interval 0.93 to 1.09. Synonymous variants: 160 observed, 161.32 expected, observed/expected ratio (o/e) 0.99, 90% interval 0.87 to 1.13.
Homologues: Orthologues: chimpanzee NEK3 (100% identical), macaque NEK3 (96% identical), pig NEK3 (86% identical), rabbit NEK3 (85% identical), guinea pig NEK3 (77% identical), mouse Nek3 (73% identical), rat Nek3 (66% identical), tropical clawed frog nek3 (54% identical). Paralogues in human: NEK5 (40% identical), NEK9 (29% identical), NEK11 (29% identical), NEK8 (26% identical), NEK2 (25% identical), NEK10 (21% identical), NEK6 (20% identical), NEK7 (20% identical).
Diseases named in the same sentence as NEK3 in open-access papers:
NEK3 is named in the same sentence as 22 diseases in open-access papers, as found by Europe PMC text mining. Sharing a sentence is not in itself a finding about the gene and the disease. The quoted sentences say what the papers report.
breast carcinoma (12 papers, 2012 to 2025). "For instance, NEK3 overexpression has been linked to increased cell motility and invasiveness in breast cancer and prostate cancer, traits that are essential for cancer metastasis." (PMID 41154634, 2025). "Overexpression of NEK3 was associated with poor prognosis in patients with gastric cancer, but better prognosis in patients with breast cancer." (PMID 37835513, 2023). "Several NEK genes have also been identified to be linked with breast cancer, such as NEK2 and NEK3 were found to be overexpressed in human breast cancer." (PMID 34834441, 2021). "Human NEK3 appears to play an important role in prolactin receptor signaling, specifically in a pathway that contributes to the progression of breast cancer and increases the motility of breast cancer cells in vitro." (PMID 31906878, 2020). "NEK3 activates Rac1 and contributes to prolactin-mediated breast cancer motility through paxillin phosphorylation." (PMID 33230144, 2020). "Phosphorylation of NEK3 at T165 modulates focal adhesion remodeling necessary for breast cancer cell migration." (PMID 33230144, 2020). "NEK3, in particular, regulates Prolactin-mediated cytoskeletal reorganization in breast cancer cells." (PMID 28476046, 2017). "Inhibition of the serine/threonine kinase, NEK3 also leads to enlarged FAs in MCF7 breast cancer cells." (PMID 28476046, 2017). "Beyond its roles in microtubule dynamics, NEK3 is also involved in various signaling pathways involved in breast cancer progression, including prolactin signaling, estrogen receptor signaling, Rho GTPase signaling, cell cycle regulation, and PI3K/AKT signaling." (PMID 41154634, 2025). "Data show the role of NEK3 in breast cancer and gastric cancer." (PMID 32294979, 2020). "Nek3, while not directly implicated in pre-B cell signaling, phosphorylates Vav1 and 2 in a breast cancer line." (PMID 22693568, 2012). "The expression of NEK2, NEK6, and NEK11 were related to colorectal cancer, NEK2, NEK3, NEK5, NEK6, and NEK8 to breast cancer, and NEK2 and NEK6 to prostate cancer." (PMID 31906878, 2020). "The PRL-mediated activation of Nek3 contributes differentially to VAV2 signaling pathways involving Rac1 and signal transducer and activator of transcription 5 and implicates Nek3 during PRL-mediated actions in breast cancer." (PMID 40160874, 2025). "In addition, NEK3 has been described as having a role in PRL-mediated cytoskeletal re-organization and breast cancer cell migration and invasion." (PMID 32294979, 2020). "Serine/threonine NIMA (Never in Mitosis A)-related family kinase NEK3 is involved in breast cancer development." (PMID 32294979, 2020). "Similarly, NEK3 and NEK2 were found to be over-expressed, in human breast cancer." (PMID 31906878, 2020).
gastric cancer (6 papers, 2020 to 2024). A primary or metastatic malignant neoplasm involving the stomach. "Immunohistochemistry and clinicopathological research revealed that NEK3 is overexpressed in gastric cancer samples when compared to their normal counterparts." (PMID 37627077, 2023). "The elevated level of NEK3 expression is substantially connected with lymph node metastases and a poor prognosis for patients with gastric cancer." (PMID 37627077, 2023). "NEK3 overexpression in gastric cancer tissues has been reported when compared with normal tissues, and this is related to poor overall survival." (PMID 32294979, 2020). "In addition, NEK3 is overexpressed in gastric cancer, which is closely related to pT stage, TNM stage, and nodal metastasis status, and can significantly reduce OS and disease-free survival in patients with gastric cancer." (PMID 35105934, 2022). "Consequently, NEK3 was suggested as a potential target and prognostic marker for gastric cancer." (PMID 37627077, 2023). "NEK3 overexpression is significantly correlated with the TNM stage, lymph node metastasis, and poor prognosis of patients with gastric cancer and can be used as an independent prognostic factor of patient survival." (PMID 38706902, 2024). "In this study, the results of the bioinformatic analysis showed that among NEKs, the expressions of NEK2, NEK6, and NEK7 are upregulated, whereas NEK3 and NEK7 are related to the poor prognosis of gastric cancer." (PMID 34419048, 2021).
ciliopathies (2 papers, 2020 to 2025). "Meanwhile, NEK3 could be a candidate gene for human ciliopathies." (PMID 33230144, 2020). "Our study suggested that NEK3 could be a candidate gene for human ciliopathies." (PMID 33230144, 2020). "The disruption in NEK3 activity, along with reduced NUP205 levels, may compromise NPC integrity and hinder nuclear-cytoplasmic transport, further implicating NEK3 as a candidate gene for ciliopathies." (PMID 41154634, 2025).
thyroid cancer (2 papers, 2022 to 2023). "NEK3 expression was shown to be downregulated in lung cancer but overexpressed in thyroid carcinoma in one report." (PMID 37835513, 2023). "High expression of NEK3 usually predicts a poor prognosis of thyroid cancer." (PMID 35368696, 2022).
alcohol addiction (1 paper, 2025). "Future studies are required to discern why Nek3 is downregulated with alcohol preference in multiple tissues and what role if any it plays in alcohol addiction." (PMID 41153338, 2025). "Nek3, Ntf3, Cux1, and Irf6 expression changes were shared across at least three tissues and may be potential biomarkers of alcohol addiction." (PMID 41153338, 2025).
medullary thyroid carcinoma (1 paper, 2020). "In the broad spectrum TMA analysis (semiquantitative and quantitative), we observed an increased expression of NEK1, NEK2, NEK3, and NEK5 in papillary and medullary thyroid carcinoma." (PMID 31906878, 2020).
papillary thyroid cancer (1 paper, 2020). "Furthermore, this work, demonstrated for the first time a high specificity and sensitivity of over-expression of NEK1 in classical and follicular variants of papillary thyroid cancer and NEK3 in tall-cell papillary thyroid cancer." (PMID 31906878, 2020).
prostate carcinoma (1 paper, 2020). A carcinoma that arises from epithelial cells of the prostate gland. "The expression of the full-length NEK3 protein is higher in prostate cancer samples compared to normal controls, but, to the contrary, normal samples have a higher expression of the shorter protein isoform." (PMID 31906878, 2020).
thyroid (1 paper, 2020). "The present study also aimed to investigate a possible role for NEK1, NEK3, and NEK5 in thyroid malignancy, and analyze their potential as diagnostic and prognostic markers." (PMID 31906878, 2020). "Here, we studied the expression of NEK1, NEK2, NEK3, and NEK5 in different types of normal and malignant tissues, using tissue microarray analysis, and identified NEKs as potential markers in thyroid malignancy." (PMID 31906878, 2020). "Once NEK1, NEK2, NEK3, and NEK5, all showed a higher level of expression in thyroid tumour tissue it was decided to expand the number of thyroid cases submitted to TMA analysis." (PMID 31906878, 2020). "Regarding mainly the expression of NEK1 and NEK3 in DTC, our results indicate that these NEKs may have an important role in thyroid malignancies, allowing to identify malignancy and aggressiveness features of DTC cases." (PMID 31906878, 2020).
thyroid tumour (1 paper, 2020). "However, the thyroid tumour tissue showed significantly higher levels of NEK3 expression when compared to normal tissues (p < 0.001-semiq.; p < 0.05-quant)." (PMID 31906878, 2020).
cancer (5 papers, 2020 to 2025). A tumor composed of atypical neoplastic, often pleomorphic cells that invade other tissues. "Identifying the direct substrates of NEK3 that mediate its effects on the cytoskeleton is a critical next step to validate it as a potential target for controlling cancer cell motility." (PMID 41154634, 2025). "Recent findings also connect NEK3 to broader cancer signaling pathways, cardiovascular function, and neuronal health, revealing its role in development and disease progression." (PMID 41154634, 2025). "Research on NEK3 has suggested its involvement in various diseases, including cancer, cardiovascular diseases, and neurological disorders." (PMID 40923186, 2025). "In cancer, NEK3 has been shown to promote tumor growth and metastasis by regulating cell migration and invasion." (PMID 40923186, 2025). "This process is fundamental to maintaining genomic stability since disruptions in NEK3 activity can lead to errors in chromosome segregation, potentially contributing to the progression of cancer." (PMID 41154634, 2025). "Additionally, understudied kinases CAMK1D, PNCK, and NEK3 have mutations with significant pan-cancer prognostic value, with PNCK being mutated frequently in LUAD and NEK3 in COAD and READ (p < 0.05)." (PMID 33205077, 2020). "NEK3-mediated phosphorylation of VAV2 enhances cytoskeletal reorganization and cell motility, which increases the invasive potential of cancer cells, further implicating NEK3 in the promotion of oncogenesis." (PMID 41154634, 2025). "The objective of the present study was to understand the involvement of four members of the NEK family (NEK1, NEK2, NEK3 and NEK5) in different types of cancers by analyzing differential expression profiles through tissues microarray (TMA) assays." (PMID 31906878, 2020). "Significant increases in the protein expression levels of NEK1, NEK2, NEK3 and NEK5, were found in colon and lung in the normal vs. cancer tissues." (PMID 31906878, 2020). "There are limited publications about the function and roles of NEK3, NEK4, and NEK5 in cancer." (PMID 37835513, 2023).
tumor (5 papers, 2017 to 2025). "Generally, EAC tissues expressed significantly higher NEK3 and NEK9 as compared to normal esophageal epithelial cells, predominantly located in cytosol in both normal and tumor cells for NEK3 and NEK7." (PMID 37835513, 2023). "Additionally, according to the UALCAN database, the mRNA expression levels of NEK2, NEK3, NEK4, NEK5, NEK6, and NEK8 were significantly positively correlated with the tumour grade, whereas that of NEK10 was inversely associated with this factor." (PMID 38706902, 2024). "Moreover, we have uncovered new genes affected by frameshift MSI events in MSI-prone tumours as well as in tumour types not frequently affected by MSI (for example, FAM129A, GMIP and NEK3 in BRCA, and DPYSL2 and ALPK2 in OV)." (PMID 28585546, 2017).
NEK3 also shares sentences with these, for which no sentence is quoted: lymph node metastases (2 papers); cardiovascular diseases (1); colorectal cancer (1); digestive system cancer (1); invasive breast carcinoma (1); lung carcinoma (1); neurological disorders (1); ovarian serous cystadenocarcinoma (1); prostate tumors (1); Stroke (1).